STAT3 (signal transducer and activator of transcription 3)
Diseases named in the same sentence as STAT3 in open-access papers (continued):
Sharing a sentence is not in itself a finding about the gene and the disease.
tumor (continued). "Because the suppression of tumor cell apoptosis further contributes to reduced treatment response, the inhibition of aberrant STAT3 activation emerges as a compelling HNSCC and CRC target." (PMID 36509291, 2022). "Production of IDO is triggered by vitamin D and prostaglandin E2 (PGE2), while its transcription is regulated by the signal transducer and activator of transcription 3 (STAT3), initiated by IL-6 from the tumor cells." (PMID 36613878, 2022). "These exosomes contain miRNA-1246, which is a tumor-promoting factor to promote cancer progression by upregulating STAT3 expression, suppressing NF-κB signaling, and mediating M2 polarization of macrophages." (PMID 35765040, 2022). "These demonstrate that the CXCR7/CXCL12 axis promotes tumor growth and metastasis by activating the STAT3 pathway in EC." (PMID 35264069, 2022). "This substance induces apoptosis and suppresses tumor cell proliferation by inhibiting signal transducer and activator of transcription 3 (STAT3) and phosphorylating nuclear factor kappa B (NF-kB)." (PMID 36278162, 2022). "The activity of STAT3 is required for embryonic development, but can also lead to tumorigenesis and tumor progression, making it a double-edged sword." (PMID 36557902, 2022). "Signal transducer and activator of transcription 3 (STAT3) is the main transcription factor mediating IL-6-induced signaling in tumor and immune cells, whereas interferon-γ (IFN-γ) signaling activates the closely related STAT1 protein." (PMID 35267462, 2022). "The IL-6/JAK/STAT3 signaling pathway is hyperactivated in many cancer types and leads to a strong suppression of the anti-tumor immune response." (PMID 36387244, 2022). "In our in vivo results, the nuclear YAP IHC staining did increase in STAT3-overexpressing tissue compared to control tumor tissue, and this result suggests that YAP translocated into the nucleus to activate downstream signaling." (PMID 35885009, 2022). "IL-6 can inhibit the maturation of DCs through the STAT3 signaling pathway, attenuating anti-tumor immunity." (PMID 36119033, 2022). "We found that the protein levels of p-STAT3 in the central region of tumor were lower compared to those in the peripheral region of tumor." (PMID 36575176, 2022). "Evidence shows that Signal Transducers and Activators of Transcription (STAT) family protein STAT3 can regulate the biological behavior of tumor cells and immune cells by mediating the extracellular signals of inflammatory mediators." (PMID 36188592, 2022). "Decreases the capacity of self-renewal and tumor initiation through STAT3 signaling inhibition and the downregulation of the stem cell self-renewal gene Nanog." (PMID 35785191, 2022). "IL-6–induced activation of the ROBO3/STAT3 pathway in CLA-like tumor cells resulted in the induction of BL-characteristic gene signatures and the acquisition of an EMT-like phenotype." (PMID 35993361, 2022). "In contrast, in TNBC, EGFR activates the JAK/STAT3 pathway by promoting the phosphorylation of STAT3, thereby facilitating the proliferation and invasion of tumor cells." (PMID 36230903, 2022). "The alternatively spliced STAT3 isoforms, full-length STAT3α and C-terminally-truncated STAT3β, have opposing function during tumor development." (PMID 35865518, 2022). "STAT3 is central to GBM pathology as it links multiple pathways that are important for the creation of this specific tumour microenvironment (TME)." (PMID 36555253, 2022). "IL-6 and G-CSF, also secreted by HPV-transformed cells, can activate STAT3 systemically, promoting the accumulation of myeloid cells, including neutrophils, which can then be recruited to the tumor microenvironment by chemotactic molecules, such as IL-8." (PMID 35804810, 2022). "Adoptive transfer of genetically engineered T cells expressing miR‐124 dampened STAT3 activity and enhanced anti‐tumour immunity." (PMID 34618359, 2022).
tumor (continued). "miR-142-3p not only restraints the generation and reduces the immunosuppressive activity of M-MDSCs, but also restores CD8+ T cells proliferation through modulating STAT3 and C/EBPβ signal pathways during tumor-induced myelopoiesis." (PMID 36569895, 2022). "STAT3 is critical in angiogenesis and regulation of the tumor microenvironment, which provides signals for differentiation or proliferation via inflammation, for instance, in the NF-κB pathway." (PMID 36061200, 2022). "The ability of IL-6/STAT3 to modulate additional tumor-promoting and tumor-suppressing pathways have been extensively investigated." (PMID 35406728, 2022). "Hyperactivation of Janus kinase (JAK)/signal transducer and activator of transcription 3 (STAT3) signaling is an attractive therapeutic target for tumor therapy." (PMID 35216314, 2022). "Regarding the promoting effect of DYRK1A on cell invasion, the results showed that DYRK1A was coexpressed with TGF-β/SMAD and STAT3 signalling components in clinical tumour samples obtained from patients with HCC." (PMID 35655269, 2022). "On the your side, STAT3 induces the anti-apoptotic proteins bcl-2, bcl-XL and survivin, which contribute to the survival of tumor cells." (PMID 36172343, 2022). "The data suggested that cytokine receptor signaling is required for the survival of tumor cells, even in the presence of JAK1/STAT3 mutations." (PMID 35406421, 2022). "Injection of EV-educated MSCs into mice with bone tumors activated STAT3 and boosted metastatic spread, demonstrating that the inflammatory loop begun by cancer EVs inside the tumour microenvironment promotes tumor cell metastatic behaviour." (PMID 36059497, 2022). "When activated HGF binds to the c-Met receptor on tumor cells, it activates several signaling pathways, including MAPK, PI3K/AKT, and STAT3, which promotes tumor growth and therapeutic resistance." (PMID 36071472, 2022). "MDSCs are recruited by CSCs through G-CSF at the tumor site where in turn they prompt CSCs stemness properties via NOTCH/STAT3 signaling cascade." (PMID 39086964, 2022). "It has been reported that constitutive phosphorylation of STAT3 in tumor tissue is correlated with poor prognosis in HCC patients." (PMID 35563493, 2022). "Such contradictory conclusions make targeting STAT3 a complicated process, and the role of STAT3 in tumor initiation and progression must be carefully studied." (PMID 36559280, 2022). "Our data demonstrate that the inhibition of STAT3 activation in COL1+ fibroblasts reduces tumor burden, whereas the constitutive activation of STAT3 promotes the development of inflammation-driven CRC." (PMID 35326623, 2022). "Previous studies have shown that XL888 (HSP90 inhibitor) combined with RFA significantly reduces STAT3 expression and phosphorylation in tumor cells, promotes tumor cell apoptosis, and ameliorates adverse effects of iRFA effectively." (PMID 36131929, 2022). "This study comprehensively demonstrated that suppression of IL-6 signaling sensitizes tumor cells to hormone therapies, suggestive of the potential therapeutic benefits of IL-6/STAT3 inhibition in luminal, hormone-dependent breast cancers." (PMID 35053592, 2022). "LncRNA PVT1 enhances the stability of STAT3 by preventing it from ubiquitin-mediated proteolysis, thus promoting tumor angiogenesis." (PMID 36010595, 2022). "Napabucasin, a class of tumor stem cell inhibitors targeting STAT3, is currently in a multicenter phase 3 clinical trial to test its anti-cancer effects." (PMID 36291659, 2022). "We demonstrate that aberrantly activated mTORC1 contributes to angiogenesis and tumor growth by regulating of the STAT3/miR-130b-3p/MBNL1 feedback loop." (PMID 36217202, 2022). "Neutrophil-derived IL-1β emerged as a novel mediator of stromal inflammation, inducing inflammatory CAF polarization and CAF-tumor cell IL-6/STAT-3 signaling in ex vivo co-cultures." (PMID 36107485, 2022).
tumor (continued). "In the suggested model, paracrine IL-6 signalling from tumour cells also activated p-STAT3 and IL-6 expression in stromal components–namely endothelial cells, CAFs (cancer-associated fibroblasts), and myeloid cells." (PMID 36429126, 2022). "The JAK/STAT3 signaling pathway, as a signaling hub, plays an important role in the tumor epithelial-mesenchymal transformation (EMT)." (PMID 35559037, 2022). "Unfortunately, EZH or HDAC suppression also induces M1 GAMs secreting IL-1β and IL-6, and activates STAT3 signals in GBM tumor cells, leading to an aggravated inflammatory response in the TME of GBM." (PMID 35572545, 2022). "Macrophages in an acidic TME tend to have an M2 phenotype: tumor-derived lactate induces M2 macrophage polarization by activating the ERK/STAT3 signaling pathway." (PMID 36050306, 2022). "Mice lacking SGPL1 in intestinal epithelial cells showed enhanced S1P levels and tumor growth, accompanied by increased STAT3 activation and inflammatory cytokine levels, which were inhibited when colonic SGPL1 levels were increased in WT mice." (PMID 35163211, 2022). "Univariate analysis showed that tumor size and p-STAT3 expression were associated with RFS, whereas multivariate analysis showed that p-STAT3(+) expression was significantly associated with a shorter RFS in patients with TNBC." (PMID 35314590, 2022). "Mechanistically, ApoC1 induces EMT by activating STAT3, eventually promoting metastasis of the tumor." (PMID 36506554, 2022). "Of these, STAT3, in particular, has been studied for its role in cancer progression, proliferation, metastasis, modulation of tumor-related immune responses and therapeutic resistance." (PMID 35053592, 2022). "STAT3 is commonly overexpressed and constitutively activated in numerous malignancies, promoting cancer, inducing cell proliferation, tumor-mediated immune evasion, angiogenesis, and cell survival." (PMID 35053370, 2022). "Supporting these data, inhibition of the AURKA/STAT3 signaling pathway promoted effective T-cell infiltration into the tumor microenvironment and improved anti-PD-1 efficacy." (PMID 35267462, 2022). "Inhibition of STAT-3 in tumor cells leads to down-regulation of its transcriptional targets belonging to the Bcl-2 family including the antiapoptotic Bcl-2, Bcl-XL and Mcl-1." (PMID 35203723, 2022). "Recently STAT3 was discovered to play a crucial role in tumor progression and prognosis of different types of cancers." (PMID 36295083, 2022). "IL-6 also promotes MDSC accumulation and inhibits anti-tumor immunity by activating the JAK/STAT3 signaling pathway, which results in increased production of ROS, NO, and PD-L1." (PMID 36246629, 2022). "In Kaplan-Meier univariate survival analysis, a part from age (P=0.006), tumor location (P=0.025), and KPS score (P=0.002), co-detection of STAT3 up regulation and presence of IDH mutation (P=0.030) remained significant prognostic factors for PFS and OS." (PMID 35844028, 2022). "Cratoxylumxanthone C showed promising anti-tumor activity in vitro by modulating STAT3 and FAK pathways." (PMID 36016565, 2022). "Both IL-10 and IL-6 induce activation of STAT3, but IL-6 induces proliferation and the production of inflammatory cytokines that promote tumor growth and is also considered to be a strong driver of many chronic inflammatory diseases." (PMID 35433880, 2022). "Increasing selective delivery of STAT3 MCs to the tumor as much as possible is of great importance for targeting survival signals and immune checkpoints directly in TNBC cells and indirectly in cancer-associated immunosuppressive cells." (PMID 35847174, 2022). "This adds another layer of complexity in understanding the role of STAT3 in NK-cell anti-tumor responses." (PMID 35865518, 2022). "We further validated the correlation between SA14 and STAT3 expression in CRC by performing IHC analysis of tumours from CRC patients (n = 18)." (PMID 35858011, 2022).
tumor (continued). "The western blot experiments found that the expression of p-STAT3 in the tumours of mice was significantly reduced after CuI treatment." (PMID 35517401, 2022). "STAT3 in carcinogenesis upregulates genes that can develop cell cycle progression, tumor survival, angiogenesis, and resistance to cell death." (PMID 35328780, 2022). "For example, FGFR4 phosphorylates and activates STAT3 to promote tumor-extrinsic immune evasion in various cancers." (PMID 35562334, 2022). "ARS is a STAT3 inhibitor and inhibits the JAK-STAT3 pathway and reduces STAT3 phosphorylation, inducing apoptosis of tumor cells." (PMID 36382024, 2022). "Deep tumor tissue, where the immune response is exhausted and tumor growth is fostered, also has enhanced IL-6/STAT3 signaling, suggesting that this pathway favors carcinogenesis." (PMID 35757757, 2022). "The direct cellular effect of STAT3 hyperactivation in tumor-infiltrating immune cells to evoke immunosuppression occurs via the inhibition of both innate and adaptive immune responses." (PMID 35053592, 2022). "In line with this and our earlier findings demonstrating the necessity of IL-6, all three inhibitors abrogated the ability of EVsMMA-MRC5 to induce IL-6/JAK/STAT3 and TGFβ signaling in A549 tumor cells, along with EMT." (PMID 36266345, 2022). "A carbamate prodrug of STAT3 inhibitor LLL12, named LLL12B, which is activated by the tumor-associated plasmin, was designed and tested in this study." (PMID 36009550, 2022). "By inserting these modifications in the mRNA of JAK1, lactylated METTL3 strengthens the pro-tumoral JAK/STAT3 pathway and enhances tumor progression of colon cancer both in vitro and in vivo." (PMID 36226054, 2022). "To test this, we examined the phosphorylation level of STAT3 (p-STAT3) using western blotting and found that TAb2 tumor indeed expressed a much higher level of p-STAT3." (PMID 35366939, 2022). "Tube formation assays confirmed that Stattic blocked the proangiogenic effect of OCLN overexpression, indicating that STAT3 was involved in OCLN‐modified modulation of tumour angiogenesis in BLCA." (PMID 35224833, 2022). "Inhibition of ERK/STAT3 signaling is known to hinder tumor growth and angiogenesis by restraining lactate-mediated M2 macrophage polarization." (PMID 36050306, 2022). "Tumor-derived PAI-1 expression is clearly associated, thereby, with increased tumorigenicity, M2 macrophage density and elevated STAT3 signaling, suggesting one possible mechanism for the protumorigenic role for this SERPIN." (PMID 35267539, 2022). "The first type of signaling, driven by tumor-derived growth factors (STAT3, IRF8, C/EBPb, Notch and NLRP3), is responsible for proliferation of immature bone marrow cells and inhibits their differentiation." (PMID 35359390, 2022). "Tc9 cell–derived IL-9 activated STAT3, upregulated fatty acid oxidation and mitochondrial activity, and rendered Tc9 cells with reduced lipid peroxidation and resistance to tumor- or ROS-induced ferroptosis in the tumor microenvironment." (PMID 35192544, 2022). "In the tumor environment, IL-6 can activate STAT3 signaling in both cancer cells and tumor-infiltrating immune cells, including macrophages, and can promote the proliferation and metastasis of cancer cells." (PMID 36547079, 2022). "Previous studies have demonstrated that the biological activities of tumor cells are regulated by multiple signaling pathways including the JAK2/STAT3 cascade." (PMID 35116094, 2022). "Immunoblot analysis of tumor tissues revealed that Ab27 decreased the phosphorylation of p27Kip1 and STAT3 and the expression of p27Kip1 and BMI1, but had a less substantial effect on the phosphorylation of extracellular signal-regulated kinase 1/2 (ERK1/2)." (PMID 35211652, 2022). "High levels of STAT3 can augment the release of tolerogenic mediators, allowing tumours to escape immune detection and decreasing immunostimulatory molecule transcription, thereby reducing innate and adaptive antitumour immunity." (PMID 36157880, 2022).
tumor (continued). "LUAD-derived cell lines, many of which display heightened STAT3 pathway activity, can represent the tumor component of the TME in vitro." (PMID 35406557, 2022). "Another study has also shown that STAT3 signaling enhances the mammosphere-forming efficiency and tumor-initiating capability of BCSCs." (PMID 36291900, 2022). "Taken together, these experimental data suggest that FDX1 functions as a tumor suppressor to influence ccRCC development at least by silencing physiological cuproptosis and triggering STAT3 signaling." (PMID 36611966, 2022). "IL-6 was used to induce STAT3 activation, resulting in the abolishment of the anti-tumor effect of Stattic in PCCs." (PMID 35288541, 2022). "In the melanoma model B16F10, RNAi-mediated expression of STAT3 in tumor tissue reduces tumor development significantly." (PMID 36476230, 2022). "Combination therapies with PD-L1 blockade or STING agonism also revealed the significance of reshaping the tumor microenvironment by STAT3 inhibition." (PMID 36080223, 2022). "STAT3 is an oncogenic transcription factor regularly activated in cancer and tumor-related myeloid cells by the IL-6." (PMID 35264191, 2022). "For example, phosphorylation of Enhancer of Zeste Homolog 2 (EZH2) results in STAT3 methylation, increasing STAT3 activity, and this interaction preferentially occurs in GSCs relative to other tumor cells." (PMID 35954407, 2022). "The abnormal expression of p-STAT3 can be found in nearly 70% of cancers, and it can be used as a marker of poor tumor prognosis." (PMID 35958524, 2022). "This has been further confirmed by experiments showing that prevention of S1PR1 activation inhibits tumour growth, metastasis and persistent STAT3 activation." (PMID 35563301, 2022). "In advanced‐stage CRC, Th17 inhibits migration of CTLs in tumor tissues by downregulating the expression of CXCR3 via the IL‐17A/STAT3 axis." (PMID 35791509, 2022). "We also investigated expression changes in TLR4, NF-κB, and STAT3 in tumor tissue and explored the impact of bacterial flora alterations." (PMID 36267958, 2022). "For example, Yang and colleagues demonstrated that blocking the mTORC1/STAT3 signaling pathway suppresses tumor angiogenesis." (PMID 36217202, 2022). "Phosphorylation and activation of STAT3 in myofibroblasts is downstream of platelet derived growth factor receptor β (PDGFRβ), an established and key regulator of the TME, linked to tumour growth." (PMID 36589727, 2022). "Abnormal STAT3 activation (such as phosphorylation) plays a crucial role in tumour cell proliferation." (PMID 34894961, 2022). "For example, IL-6 released from macrophages dominates in phosphorylating STAT3 and further promotes tumor growth and metastasis." (PMID 36405712, 2022). "PTCSC3 is the tumor suppressor lncRNA of TC and negatively regulates STAT3/INO80 to attenuate the resistance to doxorubicin that favors prognosis." (PMID 35915656, 2022). "In this model, most mutations, including APC and KRAS, occur less often than in sporadic CRC and at later stages of tumor evolution, where they promote cytokine secretion, tumor growth, and angiogenesis via the NF-κB, IL-6/STAT3, or IL-23/Th17 pathways." (PMID 35884974, 2022). "In line with the likelihood that STAT3 inhibition is induced by mc-1Stat3 in 4T1 cell-bearing mice, a reduction of primary tumor growth and a significant decrease in lung metastasis have been reported when STAT3 was knocked down in 4T1 cell-bearing mice." (PMID 35847174, 2022). "CuD has been described as a potential antitumor agent in several cancer models due to its ability to induce apoptosis through the inactivation of NF-κB and STAT3 or to produce autophagy in some tumor cell lines." (PMID 36355498, 2022).